CD4 (CD4 molecule)
Diseases named in the same sentence as CD4 in open-access papers (continued):
Sharing a sentence is not in itself a finding about the gene and the disease.
tuberculosis (continued). "By observing that HIV-induced CD4 T-cell depletion left patients vulnerable to TB and that those genetically defective for the cytokine-mediated macrophage activation pathway were similarly susceptible to tuberculosis, these investigations established its applicability to the human state." (PMID 37111338, 2023). "Stunting was associated with age ≥ 12 years, CD4 count < 200 cells/μl, tuberculosis (TB) history and history of hospitalisation." (PMID 35879693, 2022). "Importantly, a study performed in the west of China showed a positive correlation between the gut microbiota and peripheral CD4+ T cell counts in the TB patients, which highlighted the associations between gut microbiota with tuberculosis and its clinical outcomes." (PMID 36619765, 2022). "The HIV virus infects CD4 cells causing reduction of the number of immune cells which causes the body fail to control viral multiplication which increases the chance of opportunistic infection with tuberculosis being the most common opportunistic infection at HIV diagnosis." (PMID 36182998, 2022). "In this model, factors include sex, age, clinical stage and Tuberculosis (TB) co-infection were significantly associated with CD4 count (P < 0.05)." (PMID 33766121, 2021). "The human immune deficiency virus (HIV) is the strongest risk factor for latent or new infection of tuberculosis (TB) through reduction of CD4 T-lymphocytes and cellular immune function." (PMID 34812290, 2021). "The increased risk of TB in HIV- M tuberculosis co-infection has primarily focused on the defects in CD4+ and CD8+ T-cell number and function." (PMID 33995365, 2021). "The human immune deficiency virus (HIV) is the strongest risk factor for latent or new infection of tuberculosis (TB) through target reduction of CD4 T-lymphocytes and cellular immune function." (PMID 34545289, 2021). "The crucial role of the T-mediated response in protecting against M. tuberculosis infection is well demonstrated by the higher risk for a severe, treatment-resistant, and fatal TB in patients with CD4+ T lymphocyte deficiency, such as those with HIV infection." (PMID 34831976, 2021). "Well-known risk factors associated with TB-IRIS include: low CD4+ T cell count below 200 cell/mm3 at the time of clinical diagnosis of co-infection; short interval between onset of TB treatment and ART; and, disseminated tuberculosis." (PMID 31507608, 2019). "However, studies conducted in patients with CD4 count above 350cells/ mm3 suggest that incident TB is still a problem thus pointing to the fact that multiple interventions will be required in order to mitigate the burden of HIV-associated tuberculosis." (PMID 29385208, 2018). "All together, these results indicate that M. tuberculosis-specific CD4+ TCNP cells are a novel T cell subset that is associated with active TB disease." (PMID 29875774, 2018). "CD4 cell count in adults with human immunodeficiency virus (HIV) infection (PLHIV) not receiving antiretroviral therapy (ART) influences tuberculosis (TB) risk." (PMID 29259846, 2017). "Early antiretroviral therapy (ART) initiation in patients diagnosed with HIV-associated tuberculosis (TB) reduces mortality among those with the lowest CD4 counts." (PMID 27571786, 2016). "In an independent study of Mycobacterium tuberculosis-infected adolescents, activated HLA-DR+ CD4+ T cells also associate with increased TB disease risk (OR=1.387, 95% CI=1.068–1.801, P=0.014, conditional logistic regression)." (PMID 27068708, 2016). "Similarly, HIV patients with reduced CD4+ T cells are highly susceptible to tuberculosis." (PMID 26495323, 2015). "Although our study is not prospectively designed, our results also seem to suggest that earlier initiation of ART in individuals with CD4 cell count of 351-500cells/ul may be possibly beneficial in preventing development of tuberculosis, diarrhoea and weight loss." (PMID 25933356, 2015).
tuberculosis (continued). "The CD4 cell count less than 350 cells/mm3 was associated with an increased risk of TB so that the lower the CD4 cell count, the higher the risk of M. tuberculosis/HIV co-infection." (PMID 25358465, 2014). "Furthermore, clinical cure of tuberculosis has been associated with an increment in the activation potential of CD4+ and CD8+ T cells, in which both subpopulations become important for the production of cytokines such as IFN-γ and cytokines, maintaining the integrity of granulomas." (PMID 23824716, 2013). "The risk of TB-associated IRIS in HIV-infected patients is higher for those with low CD4 cell counts and high HIV viral loads, and when antiretroviral therapy is initiated early in the course of antituberculosis treatment." (PMID 21059235, 2010). "The cumulative incidence function estimated probabilities and evaluated covariate effects, including age, sex, tuberculosis status, location, baseline CD4 count, and viral load." (PMID 42205971, 2026). "Cribra orbitalia was associated with several hallmarks of compromised immune function, including fewer B cells, fewer naïve CD4+ T cells, a lower CD4+/CD8+ T cell ratio, and higher tuberculosis risk." (PMID 40668911, 2025). "The presence of CD4+ T cells is critical for the control of Mtb, as evidenced by the increased susceptibility to tuberculosis in individuals with HIV, who have depleted CD4+ T cell counts." (PMID 40282282, 2025). "CD8+ plays an important role in the clearance of tuberculosis foci, and CD4+/CD8+ reflects the state of immune balance of the organism." (PMID 40733648, 2025). "Previous studies have demonstrated that human tuberculosis results in a downregulation of Th1/Th17 and CD4 T cell populations and an increase in Th2 and regulatory T cell (Treg) responses." (PMID 40771802, 2025). "We found that SARS-CoV-2 persistence was associated with 2.5% of omicron infections among PLWH, and this rose to 3.5–4.7% among those with HIV viraemia, low CD4 counts, or a history of tuberculosis." (PMID 39902315, 2025). "Weight gain was associated with male gender, advanced HIV disease (low CD4 counts and WHO Clinical stages 3 and 4), high viral load, anaemia, and comorbid tuberculosis at presentation to the ART clinic." (PMID 40433484, 2025). "Our previous work demonstrated an enhanced antigen-specific CD4 T cell response in individuals with active tuberculosis (ATB) compared to QFT+ and QFT− controls, in response to stimulation with the MTB300 peptide pools." (PMID 40799590, 2025). "Mortality was higher among individuals who presented late with tuberculosis disease, especially those with advanced immunosuppression (CD4 <200 cells/μL)." (PMID 40748951, 2025). "Tuberculosis is oneof the commonest opportunistic infection and chances of developing tuberculosis increases with decrease CD4 cell count." (PMID 40978657, 2025). "In terms of improving the improvement rate of CD3+ T lymphocytes and CD4+ T lymphocytes, the combination of Tuberculosis Pills with conventional biomedicine shows significant advantages." (PMID 41230095, 2025). "CD4+ T cell–mediated control of tuberculosis (TB) requires recognition of macrophages infected with Mycobacterium tuberculosis (Mtb)." (PMID 40990918, 2025). "CD4+ T cells are indispensable for optimal immunity to Mycobacterium tuberculosis (M.tb), a pathogen that triggers tuberculosis (TB) in humans." (PMID 40446017, 2025). "Variation in VISITECT positivity at a given reference CD4 was associated with sex, ART status, composite tuberculosis reference standard result, country, VISITECT lot number, and operator." (PMID 39046150, 2025). "We report the case of a 28-year-old male with HIV (viral load 30 copies, CD4 count 303), active tuberculosis, and a history of resolved syphilis, who presented with severe respiratory decompensation and hypoxemia (SpO2 55%), requiring orotracheal intubation." (PMID 41010377, 2025).
tuberculosis (continued). "It should be emphasized that in tuberculosis, CD4+ T cells play a key role in the formation of an effective immune response." (PMID 40141021, 2025). "IRIS is a hyperinflammatory reaction that occurs when the immune system is recovering under antiretroviral therapy, mostly in PLWH with low CD4 counts and opportunistic infections with tuberculosis or cryptococcosis." (PMID 40606992, 2025). "Individuals with active tuberculosis disease are unable to develop sufficient cellular immune responses, despite effector CD4+ T-cells being one of the most effective components in host containment of Mtb." (PMID 40771802, 2025). "Los factores asociados con la mortalidad intrahospitalaria fueron tener un diagnóstico reciente de HIV y un bajo número de linfocitos CD4+, y presentar tuberculosis meníngea." (PMID 40865109, 2025). "People with active tuberculosis disease are unable to develop sufficient cellular immune responses, despite effector CD4+ T-cells being one of the most effective components in host containment of the Mtb." (PMID 40771802, 2025). "T-cell immunity is crucial for protection against tuberculosis, as shown by the fact that among people with HIV, loss of CD4 T-cells correlates with the risk of tuberculosis." (PMID 39747050, 2025). "La tuberculosis meníngea fue la forma extrapulmonar más frecuente y se asoció con riesgo de mortalidad, al igual que el escaso número de linfocitos T CD4+ y el diagnóstico de novo de infección por HIV." (PMID 40865109, 2025). "MAIT cells facilitate the initiation of Mtb-specific CD8+ and CD4+ Th1 responses, which are critical for controlling tuberculosis." (PMID 40825006, 2025). "The ability of CD4+ T cells to restrict Mtb growth in the lungs was entirely dependent on MHCII expression by monocyte-derived cells, indicating that cognate CD4+ T cell help to MDMs is an essential IFN-γ-independent activity in tuberculosis immunity." (PMID 40489538, 2025). "Th1 CD4+ CD27low effector T cells are an immunological biomarker of active tuberculosis and lung tissue destruction." (PMID 40724823, 2025). "It is noteworthy that incident tuberculosis exclusively occurred among PLHIV, of whom all had additional risk factors for exposure, and ongoing HIV-replication and low CD4-counts as indicators of advanced HIV-infection and marked immunosuppression." (PMID 40823191, 2025). "Ethiopia, Ghana, Tanzania, and Rwanda guidelines recommended CTX for all PWH with active tuberculosis regardless the level of CD4, with differences in other indications." (PMID 40158188, 2025). "Recently, it has been reported that patients with active tuberculosis exhibit elevated expression of PD-1 and PD-L1 in CD4+ T lymphocytes and monocytes, respectively." (PMID 41322988, 2025). "As such, these studies strongly argue that innate or other CD4/IFN-γ-independent mechanisms are also required for protection against tuberculosis." (PMID 39747050, 2025). "Baseline variables, including viral load ≥ 100,000 copies/ml, CD4 counts ≤ 200 cells/μL, WHO clinical stages 3 and 4, male gender, presence of anaemia and tuberculosis were associated with weight gain after ART initiation." (PMID 40433484, 2025). "This study evaluated the impact of this transition on AHD screening, CD4 testing uptake, tuberculosis (TB), cryptococcal meningitis (CM) management and 12‐month survival." (PMID 40657994, 2025). "An Ad5 prime–MVA boost strategy targeting the tuberculosis antigen Ag85A elicited significantly enhanced CD4+ and CD8+ T cell responses in mice compared to homologous Ad5 or MVA regimens." (PMID 41341596, 2025). "Similar relationships have been observed in studies from Nigeria, Ethiopia, and Pakistan, where patients with CD4+ counts <200 cells/μL had significantly lower Hb levels, particularly in the presence of tuberculosis or HCV co-infection." (PMID 41374357, 2025).
tuberculosis (continued). "Being Anemic, poor and fair ART adherence, advanced WHO clinical staging, missing of cotrimoxazole and isoniazid preventing therapy, low CD4 cell count, and undernutrition were significant predictors of tuberculosis incidence." (PMID 38968268, 2024). "Coinfection with TB is associated with lower CD4 levels and higher VL levels, underscoring the importance of HIV treatment facilities in diagnosing and treating both latent and active tuberculosis." (PMID 39565819, 2024). "In our previous study, we also found an association between the rs4986790-G (TLR4) allele and increased CD4 T-cell count in the group coinfected with HIV and tuberculosis." (PMID 39339847, 2024). "The importance of CD4+ T cells in controlling tuberculosis infection has been confirmed in human immunodeficiency virus and tuberculosis coinfection models." (PMID 39438693, 2024). "The combination of Urine-Xpert Ultra with AlereLAM and Sputum-Xpert Ultra rapidly diagnosed tuberculosis in 81·7% of participants overall or 87·2% of participants with CD4 counts of 200 cells per μL or lower." (PMID 39577975, 2024). "One possible explanation for physicians deferring ART at lower CD4 thresholds is their perceived risk that their patient will develop immune reconstitution inflammatory syndrome (IRIS), especially in a country where tuberculosis is so prevalent." (PMID 39028735, 2024). "Participants with CD4 counts less or equal to 50 cells/mm3 are commenced on ART at 2 weeks on tuberculosis treatment." (PMID 38720383, 2024). "Active tuberculosis is also associated with a decrease in polyfunctional and IL-2+ T cells and an increase in TNF-α+ CD4+ and CD8+ memory T cells." (PMID 39065554, 2024). "In March 2021, WHO recommendations of ART initiation within two weeks of tuberculosis treatment at any CD4 count were mainly targeted to individuals with extracranial tuberculosis." (PMID 38675837, 2024). "Correlation analysis revealed that the expression levels of IDO1 mRNA in the lungs of tuberculosis patients were negatively correlated with the infiltration of CD4+ T and CD8+ T cells." (PMID 39438693, 2024). "HIV patients, particularly those with low CD4 counts, must receive appropriate and timely tuberculosis screening, preventive therapy, and access to ART." (PMID 39058196, 2024). "Though by definition TCM CD4+ T cells are not major sources of IFN-γ, studies in humans have shown that IFN-γ production by tuberculosis antigen-specific CD4+ TCM in peripheral blood positively correlates with recovery from tuberculosis." (PMID 39664903, 2024). "The plausible reason is that the primary attack of HIV/AIDS infection is depletion of CD4 cells destruction and compromised the immune system that leads to various types opportunistic infections including tuberculosis." (PMID 38968268, 2024). "The patient’s tuberculosis status, viral load, regimen, baseline CD4 count, and location were significant contributors to death before CD4 count recovery." (PMID 39058196, 2024). "The 304 patients with four first-line drug susceptibility results were divided into two groups on the basis of gender, age, CD4 cell count, and history of anti-tuberculosis treatment to compare the differences in the resistance rates." (PMID 38675968, 2024). "The study identified a higher risk of second line ART failure among patients who had poor level of ART drug adherence, advanced WHO clinical stage at switch, CD4 count <100 cells/mm3 at switch and presence of tuberculosis co-infection." (PMID 38652716, 2024). "Patients with active tuberculosis have been shown to have a higher proportion of central IFN-γ+TNF-α+ CD4+ T cells and a lower proportion of CD8+ effector T lymphocytes." (PMID 39065554, 2024). "Thus, TB is associated with diminished CD4+ T cell response through KLRG1, with KLRG1 being a marker involved in the immunosenescence of M. tuberculosis." (PMID 38903242, 2024).
tuberculosis (continued). "The cumulative incidence of patients with prevalent tuberculosis was lower than those with tuberculosis in patients with recovered CD4 count." (PMID 39058196, 2024). "Clinical objectives were variably met at re-engagement: 98% were re-initiated the same day, 50% had a CD4 done, and 45% received tuberculosis prevention." (PMID 38538754, 2024). "The mean CD4, CD8 T lymphocyte count and CD4/CD8 at the start of tuberculosis treatment in HIV patients who initiated tuberculosis therapy were in the High CD4 trajectory were, respectively, 433.74 cells/mm3, 1179.14 cells/mm3, 0.42." (PMID 38478483, 2024). "The 93 patients with four first-line and eight second-line drug susceptibility results were divided into two groups on the basis of gender, age, CD4 cell count, and status of anti-tuberculosis treatment to compare the difference in the resistance rates." (PMID 38675968, 2024). "Results showed that the patient’s tuberculosis status, viral load, regimen, baseline CD4 count, gender, WHO stage, and location were significant contributors to death before CD4 count recovery." (PMID 39058196, 2024). "In the SAPiT-1 study, initiation of ART during tuberculosis treatment in patients with CD4 counts < 500 cells/μL reduced mortality by 56% compared with starting ART after tuberculosis treatment completion." (PMID 38675837, 2024). "In previous studies, we observed the correlation between CD4 T-cell count and genotypes for patients coinfected with tuberculosis and HIV." (PMID 39339847, 2024). "Early studies yielded different views on the relevance of different subsets of CD4+ T cells in the anti‐tuberculosis effect." (PMID 39439490, 2024). "Co-infection of human immuno deficiency virus with hepatitis B virus or hepatitis C virus, tuberculosis and CD4+T-cell count below 200 cells/mm3 were predictors of severe hepatotoxicity." (PMID 38605149, 2024). "Being Anemic, poor and fair ART adherence, advanced WHO clinical staging, cotrimoxazole preventive therapy, isoniazid preventing therapy, low CD4 cell count, being stunting and underweight were significant predictors of tuberculosis incidence." (PMID 38968268, 2024). "tuberculosis-CFP-specific CD4+ T-cell line from infected C57BL/6 mice to identify antigens linked with the early control of M. tuberculosis infection." (PMID 38461350, 2024). "Tuberculosis was the predominant OI in the group with CD4 cell count ≤ 200 cells/m3 in both Cohort 1 (26.8%) and Cohort 2 (27.9%), p = 0.039." (PMID 38299523, 2024). "Factors such as undiagnosed HIV status, low CD4 + cell counts, tuberculosis, and co-infections are among the common predictors of mortality among hospitalized PLHIV." (PMID 38388345, 2024). "Antigenuria was found to be a good marker of CM in the study population, and it was associated with low CD4+ cell count, WHO stage III/IV, and tuberculosis." (PMID 39728839, 2024). "Age and CD4 count at presentation were similar to our study (35 years and 74 cells/mL), but tuberculosis coinfection was more frequent (37% vs 5.2%)." (PMID 39568658, 2024). "Based on much of the evidence for rapid ART, in March of 2021, the WHO recommended that ART should be started within two weeks of tuberculosis treatment at any CD4 count, especially for those with CD4 ≤ 50 cells/μL." (PMID 38675837, 2024). "Anemia, poor and fair ART adherence, WHO clinical staging (III/IV), children who missed take cotrimoxazole and isoniazid preventing therapy, CD4 cell count (<200 cells/mm3), undernutrition were significant predictors of tuberculosis incidence." (PMID 38968268, 2024). "The risk of treatment failure was higher in patients who were in an advanced WHO clinical stage, CD4 count <100 cells/mm3, and presence tuberculosis co-infection." (PMID 38652716, 2024). "Mtb-HSP-induced monocytes and CD4+T cell apoptosis were significantly lower in tuberculosis than in SA and in healthy subjects." (PMID 36982159, 2023).